EDN1 (endothelin 1)
Diseases named in the same sentence as EDN1 in open-access papers (continued):
Sharing a sentence is not in itself a finding about the gene and the disease.
Peri-Implantitis (3 papers, 2024 to 2025). An inflammatory process with loss of supporting bone in the tissues surrounding functioning DENTAL IMPLANTS. "Endothelin-1 (ET-1) has been identified as a potential early biomarker in peri-implant diseases, including mucositis and peri-implantitis, indicating the presence of early inflammatory activity." (PMID 41373620, 2025). "Levels of endothelin-1 (ET-1) have been shown to be elevated in cases of peri-implant mucositis and peri-implantitis in comparison with healthy sites, thus supporting its potential as an early biomarker." (PMID 41373620, 2025).
pregnancy disorder (3 papers, 2017 to 2022). A disorder that is related to pregnancy. "Although neonatal and pregnancy diseases have shown in-vivo and ex-vivo alterations in numerous soluble endothelial markers, including adhesion molecules, tissue factor (TF), and endothelin 1 (ET-1), currently, little is known about the endothelial profile of preterm infants." (PMID 35625922, 2022).
prostate tumor (3 papers, 2014 to 2022). "IL-1β can also induce the expression of endothelin 1 (ET-1), which is implicated in prostate tumor progression." (PMID 32635472, 2020). "Prostate tumour cells hyper-secrete endothelin-1 (ET-1), that regulates osteoblast function and contributes potently to PCIBP." (PMID 36258057, 2022). "In this study, we also detected the increase in EDN1 protein expression in breast, cerebrum, liver, and prostate tumors." (PMID 24416389, 2014).
prurigo nodularis (3 papers, 2016 to 2022). Prurigonodularis (PN) is a skin disease in which hard crusty lumps are formed on the skin that itches intensely. "The potent pruritogen endothelin-1 (ET-1) is implicated in histamine-independent pruritus in mice and humans, especially in skin diseases with increased pruritus such as AD and prurigo nodularis, in which antihistamines are hardly effective." (PMID 32903402, 2020).
renal hypertension (3 papers, 2013 to 2022). Hypertension caused by the kidney's hormonal response to narrowing or occlusion of the renal arteries. "The pathological mechanism of renal hypertension is complex, including activation of the sympathetic nervous system (SNS) and renin-angiotensin-aldosterone system (RAAS), oxidative stress, increased endothelin-1 (ET-1), and inflammation." (PMID 37675019, 2022).
serous ovarian cancer (3 papers, 2022 to 2024). "Endothelin-1 (ET-1) regulates the communication between cancer and stroma and facilitates the progression of serous ovarian cancer (SOC)." (PMID 38777849, 2024). "In high-grade serous ovarian carcinoma (HG-SOC), endothelin-1 (ET-1)/endothelin A receptor (ETAR) signaling promotes EMT driving tumor progression." (PMID 35477522, 2022).
stenosis (3 papers, 2008 to 2022). "Under the influence of different mediators, mainly endothelin-1 and PDGF, vascular smooth muscle cells migrate to the intima, proliferate and change their phenotype to become myofibroblasts that further proliferate and produce extracellular matrix proteins, increasing the vascular stenosis." (PMID 35629030, 2022).
ulcerative colitis (3 papers, 2018 to 2024). An inflammatory bowel disease involving the mucosal surface of the large intestine and rectum. "Thus, it is confirmed that ICC, SCF, ghrelin, and endothelin-1 are associated with ulcerative colitis." (PMID 29694505, 2018).
Vasovagal syncope (3 papers, 2015 to 2025). A vasovagal episode or vasovagal syncope is the most common form of reflex syncope. "A previous study looked into gene variant encoding for endothelin-1 and ETAR and identified an endothelin-1 with a potential role in the pathophysiology of vasovagal syncope, which, like orthostatic intolerance, is characterized by a dysregulated autonomic nervous system." (PMID 40001603, 2025).
Acidosis (2 papers, 2024). Abnormal acid accumulation or depletion of base. "Acidosis also promotes systemic and renal production of endocrine factors such as aldosterone, angiotensin II, or endothelin 1 (ET1)." (PMID 38448728, 2024). "Acidosis increases endothelin-1 and aldosterone production, furthering CKD progression and cardiovascular pathology." (PMID 38891884, 2024).
atrial septal defect (2 papers, 2014 to 2020). Interauricular communication is a congenital malformation characterized by a communication between the atrial chambers of the heart. "The study aimed to assess the level of plasma Endothelin-1 (ET-1) in patients before and after transcatheter closure of atrial septal defect (ASD) and to evaluate the usefulness of measuring ET-1 levels for the diagnosis and selection of candidates for ASD closure." (PMID 25099217, 2014).
auriculocondylar syndrome (2 papers, 2016). "For example, auriculocondylar syndrome is caused by impaired Endothelin-1 (Edn1) signaling, and Alagille syndrome is caused by defects in Jagged-Notch signaling." (PMID 27880803, 2016). "For example, Auriculocondylar syndrome is caused by impaired Endothelin-1 (Edn1) signaling and Alagille syndrome is caused by defects in Jagged (Jag)-Notch signaling." (PMID 27880803, 2016).
autonomic dysfunction (2 papers, 2018 to 2024). "Endothelin-1 and autonomic dysfunction, which are known to be involved in poor peripheral blood circulation, may partially affect the pathogenesis, persistence, and worsening of a disease." (PMID 29385996, 2018).
cerebral malaria (2 papers, 2008 to 2016). A sequestration of Plasmodium falciparum in the brain, which can cause coma and/or seizures. "The vasoactive compound endothelin-1, a key participant in many inflammatory processes, likely mediates vascular and cognitive dysfunctions in cerebral malaria." (PMID 27031954, 2016). "Furthermore, exogenous endothelin-1 administration to P. berghei NK65-infected mice, a model generally regarded as a non-cerebral malaria negative control for P. berghei ANKA infection, led to experimental cerebral malaria-like memory deficits." (PMID 27031954, 2016).
chronic venous insufficiency (2 papers, 2016 to 2025). Chronic form of venous insufficiency (disease). "We previously showed that Aminaphtone, a drug used in the treatment of chronic venous insufficiency, modulates several vasoactive factors, such as endothelin-1 and adhesion molecules." (PMID 27508230, 2016).
complex regional pain syndrome (2 papers, 2008 to 2019). A chronic pain syndrome characterized by a disproportionate spontaneous or stimulus-induced pain, accompanied by a variably mixed myriad of autonomic and motor disorders including symptoms such as swelling, allodynia, skin blood supply and trophic disturbances. "There is a network centered on GNG7, that may be involved in connectivity/signaling, comprising HTR2A, EDN1, PNOC (involved in pain signaling) and CALCA (involved in Reflex Sympathetic Dystrophy and Complex Regional Pain Syndrome)." (PMID 30755720, 2019).
dermatitis (2 papers, 2023 to 2025). An inflammatory process affecting the skin. "Other cell signaling pathways including cell cycle and NF-kB pathway (CCND1), autophagy (ATG16L2, ATG10), wnt/β-catenin (APC, GSK3β) and angiogenesis (EDN1) regulating genes were associated with RT related acute mucositis and dermatitis." (PMID 37954025, 2023).
elephantiasis (2 papers, 2018 to 2022). Enlargement of an area of the body due to obstruction within the lymphatic system and the resulting accumulation of lymph. "Further analyses showed strong association of a mutation (M196A) in human tumor necrosis factors (TNF) receptor-II with hydrocele development, while the A288S mutation of endothelin-1 (ET-1) correlated with low ET-1 1 plasma levels and elephantiasis." (PMID 30538723, 2018).
endometrial cancer (2 papers, 1995 to 2023). Primary or metastatic malignant neoplasm involving the endometrium (mucous membrane that lines the endometrial cavity). "In our study, a low activity was also observed for miR-130b-3p, miR-4319, and miR-379-5p in the early stage of endometrial cancer, which may be associated with the highest EDN1 expression in G1 cancer." (PMID 36542159, 2023). "Published experimental works focus on their effects on endothelin-1 and endothelin receptors, but little is known about endothelin-3, particularly in endometrial cancer." (PMID 36542159, 2023). "In this study, EDRNA was overexpressed, especially in G1 cancer same as EDN1, while EDNRB levels were decreased in endometrial cancer compared to the control." (PMID 36542159, 2023). "In our study, EDN1 showed a significant increase in expression regardless of the endometrial cancer grade in both the microarray and RT-qPCR experiments." (PMID 36542159, 2023). "EDN1 showed overexpression as endometrial cancer progressed, while changes in EDN2 levels were not statistically significant." (PMID 36542159, 2023). "EDN1 and EDNRA were overexpressed regardless of endometrial cancer grade, which may be due to the lack of regulatory effect of miR-130a-3p and miR-485-3p, respectively." (PMID 36542159, 2023).
epilepsy (2 papers, 2017 to 2025). A brain disorder characterized by episodes of abnormally increased neuronal discharge resulting in transient episodes of sensory or motor neurological dysfunction, or psychic dysfunction. "Epilepsy gene group indentified top-ranking signaling pathways that were associated with retinoic acid receptor (6 genes), endothelin-1 (6 genes), Gq alpha protein (5 genes) and corticotropin releasing hormone (5 genes)." (PMID 28904337, 2017).
glomerulonephritis (2 papers, 2021 to 2025). A renal disorder characterized by damage in the glomeruli. "The correlation between initial plasma endothelin 1 concentrations and initial serum total protein concentrations in the focal and segmental glomerulonephritis cohort was negative (n = 30; p = 0.03; r = −0.38)." (PMID 41517469, 2025).
intracranial aneurysms (2 papers, 2022). "Several of these target genes have been reported to be closely related to the formation, growth and rupture of intracranial aneurysms, including transglutaminase 2 (TGM2), epiregulin (EREG), endothelin-1 (EDN1) and alpha 1 type IV collagen (COL4A1)." (PMID 35242102, 2022).
liver cancer (2 papers, 2020 to 2023). An epithelial or non-epithelial malignant neoplasm that arises from the liver. "The overexpression of EDN1 in zebrafish could promote cell proliferation, invasion, and metastasis and induce liver cancer." (PMID 32089682, 2020).
non-small cell lung carcinoma (2 papers, 2021 to 2023). A group of at least three distinct histological types of lung cancer, including non-small cell squamous cell carcinoma, adenocarcinoma, and large cell carcinoma. "However, in our model no fibrosis was observed, potentially due to the length of observation time; moreover, Edn1 is also a potent vasoconstrictor peptide, and its dysregulation has been implicated in coronary microvascular dysfunction, non-small cell lung cancer development and progression." (PMID 34872491, 2021).
oral lichen planus (2 papers, 2013 to 2022). Oral lichen planus is a chronic inflammatory oral condition of unknown aetiology characterized by T-cell-mediated chronic immune response and abnormal epithelial keratinization cycle. "For example, protein Endothelin-1 (P05305), ranked the 728th, has been implicated in cancer, and could be a good salivary biomarker for OSCC development in oral lichen planus patients." (PMID 24324552, 2013).
pneumonia (2 papers, 2019 to 2025). An acute, acute and chronic, or chronic inflammation focally or diffusely affecting the lung parenchyma, caused by an infection in one or both of the lungs (by bacteria, viruses, fungi, or mycoplasma.). "Additionally, the precursor peptide ET-1 of EDN1 gene is correlated with the severity of pneumonia, ICU admission, and mortality." (PMID 31167651, 2019).
prediabetes (2 papers, 2024). "Pulmonary vascular function, including the roles of nitric oxide (NO), prostacyclin (PGI2), endothelin-1 (ET-1), thromboxane A2 (TxA2) and thrombospondin-1 (THBS1), is discussed in the context of T2DM and prediabetes." (PMID 39050565, 2024).
proliferative diabetic retinopathy (2 papers, 2018 to 2020). Advanced retinopathy due to diabetes mellitus characterized by the formation of new vessels in the retina. "Jinzi Zhou had reported elevated EDN1 in vitreous of patients with proliferative diabetic retinopathy (PDR)." (PMID 32016117, 2020). "Through standard immunohistochemical techniques, we labeled membranes to explore the distribution of endothelin-1 and endothelin receptor B, comparing proliferative diabetic retinopathy and idiopathic epiretinal membranes." (PMID 29351334, 2018). "Immunohistochemistry and quantitative analysis of cross-sectional membranes showed significantly higher endothelin-1 labeling in proliferative diabetic retinopathy membranes compared to idiopathic membranes (p<0.05)." (PMID 29351334, 2018). "Epiretinal membrane formation in proliferative diabetic retinopathy involves higher tissue levels of endothelin-1 and fibroblastic activity." (PMID 29351334, 2018). "Furthermore, endothelin-1, endothelial and fibroblastic staining appear to be correlated, suggestive of endothelial-to-mesenchymal transition in proliferative diabetic retinopathy." (PMID 29351334, 2018).
retinal (2 papers, 2016 to 2025). "MS and FS share further aspects, such as increased rigidity of the retinal vessels, increased endothelin-1 plasma level and increased frequency of retinal gliosis-like alterations." (PMID 27307797, 2016).
retinopathy of prematurity (2 papers, 2021 to 2023). A bilateral retinopathy characterized by neovascularization, scarring, retinal detachment, and eventually blindness. "The aim of this study was to investigate the association between selected polymorphisms of nitric oxide synthetase (eNOS) and endothelin-1 (EDN-1) with the occurrence and progression of retinopathy of prematurity (ROP)." (PMID 36829141, 2023).
Shock (2 papers, 2012 to 2015). The state in which profound and widespread reduction of effective tissue perfusion leads first to reversible, and then if prolonged, to irreversible cellular injury. "Furthermore, septic shock is also associated with an increased level of platelet-activating factor, thromboxane A2, leukotrienes, macrophage inflammatory protein-1, prostaglandin E2 (PGE2), cyclooxygenase (COX)-2 mRNA and endothelin-1 (ET-1)." (PMID 25288367, 2015).
squamous cell carcinoma (2 papers, 2014 to 2019). A carcinoma arising from squamous epithelial cells. "The authors clearly demonstrated stem cell factor and endothelin-1 expression in the neoplastic squamous cells, which may have led to the development of melanocytic colonization in squamous cell carcinoma." (PMID 24396444, 2014).
Sudden cardiac death (2 papers, 2023). "WHtR: Waist-to-height ratio; NT-proBNP: N-terminal brain natriuretic pro-peptide; ADMA: Asymmetric dimethylarginine; ET1: Endothelin 1; FFM: Fat-free mass; BF%: Body fat percentage; FM: Fat mass; SCD: Sudden cardiac death; CAVI: Cardio-ankle vascular index; CVD: Cardiovascular disease." (PMID 37303408, 2023).
Takotsubo cardiomyopathy (2 papers, 2021 to 2022). "Jaguszewski and colleagues reported reduced levels of 125a-5p microRNA which were associated with increased levels of plasma endothelin-1 in patients who experience Takotsubo cardiomyopathy." (PMID 36551766, 2022).
tuberculosis (2 papers, 2019 to 2021). A chronic, recurrent infection caused by the bacterium Mycobacterium tuberculosis. "EDN1 is a well-known vascular regulator; its specific role in infectious diseases, including tuberculosis, are currently being elucidated." (PMID 34042560, 2021). "Edn1 is a well-known vascular regulator; however, its particular roles in infectious diseases including tuberculosis are only beginning to be elucidated." (PMID 30669987, 2019).
Ureteral obstruction (2 papers, 2008 to 2025). Obstruction of the flow of urine through the ureter. "The authors also determined ET-1 levels in the blood and kidneys in endothelin-1 knock-out mice and performed histopathological analysis after unilateral ureteral obstruction." (PMID 41153763, 2025).
Uterine leiomyoma (2 papers, 2015 to 2021). The presence of a leiomyoma of the uterus. "The EDN1 reveals an anti-apoptotic effect in rat uterine leiomyoma ELT3 cells." (PMID 25932638, 2015).
uterine tumor (2 papers, 2014 to 2022). "EDN1 overexpression was observed in 80 malignant tumors, which represented 10 tumor types, including breast, cerebrum, colon, liver, lung, prostate, and uterus tumors." (PMID 24416389, 2014).
acute liver failure (1 paper, 2020). Rapid deterioration of liver function causing encephalopathy and coagulopathy. "Analysis of human genes of primary human hepatic sinusoidal endothelial cells and patient tissues after APAP overdose induced acute liver failure showed that ICAM1 and EDN1 obviously increased, further supporting our findings." (PMID 32550899, 2020).
alcoholic liver diseases (1 paper, 2020). A disorder caused by damage to the liver parenchyma due to alcohol consumption. "In alcoholic liver diseases model, NOXs induced endothelin-1 in the liver sinusoidal endothelial cells, which can be attenuated by transfection of the p47phox siRNA30." (PMID 32001731, 2020).
angiomyolipoma (1 paper, 2018). A neoplasm with perivascular epithelioid cell differentiation often associated with tuberous sclerosis. "We have analyzed the expression of EDN1 and of its receptors EDNRA and EDNRB in primary LAM cells as well as in a TSC2 mutated cell line derived from an angiomyolipoma." (PMID 30279475, 2018). "In this study, we explored the role of EDN1 and of its receptors in LAM-derived primary cells and in angiomyolipoma-derived cells lines." (PMID 30279475, 2018).
autoimmune myocarditis (1 paper, 2022). Autoimmune myocarditis is an autoimmune disease that affects the heart. "In addition, it suppressed the endothelin-1 (ET-1) and myocardial MAPK yielding the progression of experimental autoimmune myocarditis." (PMID 36703744, 2022).
Binswanger’s disease (1 paper, 2018). "Clinical data indicated that circulating endothelial cells (CEC) and production of endothelin-1 (ET-1) and malondialdehyde (MDA) in the internal jugular vein of Binswanger’s disease patients were dramatically increased after AR treatment, compared to the negative control." (PMID 29883402, 2018).
bladder overactivity (1 paper, 2023). "Another role of EDN1 in the female reproductive tract has been extensively researched in the setting of a potential therapeutic target for the treatment of bladder overactivity, although with various success." (PMID 37109658, 2023).
cardiopulmonary diseases (1 paper, 2022). "One of the EDN1 missense polymorphisms, rs5370 G/T, has strongly been associated with cardiopulmonary diseases." (PMID 36141455, 2022).
cardiotoxicity (1 paper, 2014). Toxicity that impairs or damages the heart. "Fifth, most of the findings in the human studies were not confined to patients experiencing cardiotoxicity, as only NT-proBNP and endothelin-1 were higher in patients with cardiotoxicity." (PMID 25186061, 2014).
Chagas cardiomyopathy (1 paper, 2025). A disease of the cardiac muscle developed subsequent to the initial protozoan infection by trypanosoma cruzi. "Interestingly, TNF and endothelin-1 are well-established biomarkers of pathogenesis in experimental T. cruzi infection and indicators of severity in Chagas cardiomyopathy." (PMID 40936920, 2025).
cleft palate (1 paper, 2018). Cleft palate is a fissure type embryopathy that affects the soft and hard palate to varying degrees. "In fact, several of the Shh target genes identified here in the cNCC, including Adamts9, Edn1, Dlg1, and Efnb1, are already implicated in cleft palate pathogenesis by existing mouse models." (PMID 29945554, 2018).
CNS demyelinating diseases (1 paper, 2020). "Therefore, the results of this study strongly suggest that endothelin-1 levels significantly contribute to the pathogenesis of immune-mediated CNS demyelinating diseases by promoting inflammatory immune responses following the neurotrophic TMEV infection." (PMID 33069239, 2020).